HSP90B1 (heat shock protein 90 beta family member 1)
Diseases named in the same sentence as HSP90B1 in open-access papers (continued):
Sharing a sentence is not in itself a finding about the gene and the disease.
cancer (continued). "However, in response to oncogenic factors, HSP90B1 is expressed at elevated levels in cancer cells, thereby enhancing their survival capacity and ultimately contributing to cancer initiation and progression." (PMID 39149033, 2024). "The inhibition of HSP90B1 in targeted therapy may impede the correction of misfolded oncoproteins, thereby inducing cancer cell death." (PMID 38665430, 2024). "Hence, it is imperative to explore the regulatory functions and molecular mechanisms of HSP90B1, offering new perspectives and rationales for cancer diagnosis and therapy." (PMID 38243263, 2024). "In the present study, we employed multi-omics analyses and cohort validations to explore the dynamic expression of HSP90B1 in pan-cancer and comprehensively evaluate HSP90B1 as a novel biomarker that hold promise for precision cancer diagnostics and therapeutics." (PMID 38243263, 2024). "This study provides a rationale for HSP90B1 targeted cancer diagnosis and therapy in future." (PMID 38243263, 2024). "Metabolic abnormalities and uncontrolled angiogenesis are two important features of malignant tumors, and the occurrence of these two events may involve the regulation of HSP90B1." (PMID 38711062, 2024). "HSP90B1 is abundantly deposited in cancer cells and can be bound to tumors." (PMID 38243263, 2024). "The promotion of high levels of HSP90B1 on NPC cell proliferation, glycolysis, and angiogenesis may be the main cause of cancer cell metastasis." (PMID 38711062, 2024). "However, TGM2_v2 mediated the repression of over 20% of these cancer-related gene transcripts, among which is HSP90B1, and induced the expression of MUC1." (PMID 37160910, 2023). "HSP90B1 is crucial for the chaperoning of various proteins, including Toll-like receptors (TLRs), integrin subunits, and wnt co-receptor low-density lipoprotein receptor-related protein 6 (LRP6), that have been linked to immune response and cancer development." (PMID 36291587, 2022). "Various immuno-histochemistry studies report that HSP90B1 protein is significantly overexpressed in a variety of malignancies, including breast, lung, colorectal, oral, oesophageal, and gastric cancers, indicating a connection with cancer development." (PMID 36291587, 2022). "Our data showed that HSP90B1 have a critical role in cancer signaling pathway." (PMID 32537125, 2020). "The ER chaperones GRP78/BiP and GRP94/HSP90B1 are increased in many different cancers." (PMID 28540288, 2017). "In addition to Nanog, other stemness genes including Notch2, CTNNB1 and Hsp90B1 are also important to CSCs and cancer cells." (PMID 27917123, 2016). "Notably, methylation of HSP90B1 emerged as a protective factor in several cancer types." (PMID 38243263, 2024). "Furthermore, GEPIA2 analysis revealed that HSP90B1 expression levels were significantly correlated to the clinical stage of the following cancer types: COAD (p = 0.0255), KICH (p = 0.0174), KIRC (p = 0.00213), OV (p = 0.00271), SKCM (p = 0.032), and TGCT (p = 0.0015)." (PMID 36291587, 2022). "Thus, HSP90B1 has a significant relationship with cancer growth and metastases." (PMID 36291587, 2022). "Therefore, upregulation of HSP90B1 by MS13 treatment may contribute to the inhibition of cancer growth and metastasis in AIPC." (PMID 34366863, 2021). "One of the most studied subfamilies in cancer, the HSPC subfamily (also known as HSP90) presented 2 amp-CNV altered members (HSP90AB1, and TRAP1), and just one del-CNV (HSP90B1)." (PMID 38816397, 2024). "HSP90B1, a member of the HSP90 family, plays a role in sustaining cancer cell survival by facilitating ERBB2-dependent downstream signalling pathways." (PMID 39063109, 2024). "Consequently, targeting HSP90B1 may prove effective in diagnosing and treating cancer." (PMID 39149033, 2024). "Among 36 genes, MMP1, HSP90B1, PTK2, MMP3, NOTCH1 and CDH5 had higher methylation status at pan-cancer level." (PMID 38694917, 2024).
cancer (continued). "The co-essential relationships between HSP90B1, CCDC134 and OST-A across the DepMap panel of >1000 cancer cell lines are likely a consequence of their shared role in IGF1 signaling, known to be a universal driver of cell growth and survival." (PMID 39509507, 2024). "This study also found that HSP90B1 was highly expressed in NPC cells and cancer tissues." (PMID 38711062, 2024). "AR, MIF, HSP90B1, and MAOA were expressed in more than 50% of cancer cells with high expression levels and may have potential therapeutic targets." (PMID 36452480, 2022). "Fifteen members of cancer pathways, including FOS, TGFα, FZD8, MMP1, laminin subunit gamma 2, PTGS2, laminin subunit beta 3, ITGA2, laminin subunit alpha 3, VEGFC, WNT2B, heat shock protein 90 beta family member 1, WNT5B, FGF5 and WNT3A, were up-regulated in the MC group." (PMID 30482199, 2018). "Seven out of 52 genes (GSTP1, HSP90B1, HSPB1, PFN1, RAP1A, SFN, YWHAZ) were assigned to KEGG pathways in cancer, cell migration and cell cycle, and in signaling networks involved in proliferation, cellular motility, apoptosis, cell adhesion, angiogenesis and genetic integrity." (PMID 30157864, 2018). "Another 6 genes, SUB1, SLC2A1, CTNNB1, ACTB, HSP90B1, and CLTC were selected from the remaining unknown migration-related genes in order to confirm their relationship with cancer cell migration." (PMID 28640862, 2017). "Although the involvement of HSPB1 activity in cancer growth has been well described in recent years, the role of HSP90B1 in the pathogenesis of PCOS has not been well investigated." (PMID 27046189, 2016). "In addition, the HSP90B1 inhibitor PU-WS13 demonstrated significant efficacy in suppressing cancer cell proliferation in both leukemic and solid tumor cells, and remarkably reduced the expression of the cancer cell surface immune checkpoint PD-L1." (PMID 38243263, 2024). "However, a comprehensive understanding of HSP90B1’s role in cancer remains lacking." (PMID 38243263, 2024). "The analysis of 46 immunostimulatory genes in pan-cancer showed that HSP90B1 expression was positively correlated with CD40, CD270, PVR, MICB, ULBP1, TNFSF4, while exhibiting a negative correlation with CD48 and CD40LG in most cancers." (PMID 38243263, 2024).
infection (45 papers, 2010 to 2025). The state of being infected such as from the introduction of a foreign agent such as serum, vaccine, antigenic substance or organism. "Among the HSP90 gene family members, with the exception of hsp90ab1 and hsp90b1, which displayed an increasing trend at the onset of infection, the remaining members showed a significant decreasing trend following I. multifiliis infection." (PMID 39596645, 2024). "HIF1α, which is a key regulator of transcriptional signaling in hypoxic conditions, was induced following infection with either virus, as were HSP90B1 and DBF4, which are mediators of the unfolded protein response and cell cycle arrest, respectively." (PMID 33405202, 2021). "For the infection of C. albicans WO-1, it will bring about more protein folding of host cell by higher expression of HSP90B1 with phosphorylation." (PMID 30769958, 2019). "More work is needed to elucidate the complete role of HSP90B1 in the human immune response to infection." (PMID 30550567, 2018). "Our data reveals their presence and an increase in HSP90 and Hsp90b1 following infection." (PMID 40523037, 2025). "The infection progression associated with essential epigenetic modifications in two strains of C. albicans such as ARRB2, CDH1, HSP90B1, EGFR and ERBB2, and host miRNA repressing on pathogens genes are mostly identified in core HPCNs by our systems biology approach." (PMID 30769958, 2019). "According to our analysis above, the difference between YN13 and YN144 in replication ability might be due to the difference between the two PEDV-infection groups in alterations of eIF4G1, hnRNPA1, HSP90B1, HSP90AB1, HSPA8, DNAJA1, and DNAJC10 in jejunums of pigs." (PMID 27916855, 2016). "In primary NHBE cells, pre-infection priming with TG enhanced expression of the ER stress genes (DDIT3, HSPA5 and HSP90B1), relative to the DMSO control, before and during RSV infection in a TG dose-dependent manner." (PMID 33546185, 2021). "In response to pathogen infection, the receptors such as EGFR, ERBB2, CDH1, HSP90B1, and TJAP1 at the host membrane interact with pathogen cell wall proteins to start inducing endocytosis." (PMID 30769958, 2019). "Previous studies indicate that orf19.1816 will induce endocytosis by binding host cell receptors such as ERBB2, HSP90B1, CDH1 and CDH2 so that it will be considered as an infection initiation." (PMID 30769958, 2019). "In this study, HSPA5, HSPA1B, HSP90B1 and HSPA6 were up-regulated at 24 hpi to various degrees following CPIV3 -infection of MDBK cells." (PMID 31101113, 2019). "In the infection progression of C. albicans SC5314, orf19.1816 (ALS3) plays a significant role in cell adhesion and endocytosis induction by interacting with EGFR, ERBB2 (HER2), CDH1 (E-cadherin), HSP90B1 and TJAP1 (TJP4)." (PMID 30769958, 2019). "Following infection at 10 dpi, six of the DEGs were immune genes (GAL1, GAL2, GAL7, ABCB1, LEPR and SNED1) and two were involved in NOD-like receptor signaling pathway (K60 and HSP90B1), all were upregulated in expression in line 63 birds." (PMID 31578366, 2019). "Subsequently, when HSP90B1 with GAPDHP24-induced phosphorylation further triggers the regulation of TF ETS1, HSP90B1 with ubiquitination will not activate TF ETS1 in the infection of C. albicans SC5314." (PMID 30769958, 2019).
immune disorders (2 papers, 2025). "For instance, small molecule inhibitors targeting HSP90B1 or agents that modulate SYNCRIP’s RNA-binding activity could be explored to simultaneously disrupt metabolic adaptation and correct immune dysfunction in EMs." (PMID 41168872, 2025).
psychiatric disease (2 papers, 2021 to 2025). "However, only two genes (i.e., HSP90B1 and NCAM1) show the same directional effects across all the 14 psychiatric disorders and the others display opposite directional effects on two or more disorders." (PMID 34895209, 2021).
HSP90B1 also shares sentences with these, for which no sentence is quoted: autoimmune disease (13 papers); colon cancer (12); liver cancer (11); multiple myeloma (11); viral infection (10); rheumatoid arthritis (8); cervical carcinoma (7); colitis (7); COVID-19 (7); neuroblastoma (7); Sepsis (7); adenocarcinoma (6); glaucoma (6); lupus (6); pancreatic cancers (6); Autoimmunity (5); metastatic cancers (5); renal cell carcinoma (5); bacterial infection (4); breast tumor (4); esophageal cancer (4); malaria (4); colorectal (3); Crohn disease (3); esophageal adenocarcinoma (3); esophageal squamous cell carcinoma (3); head and neck cancer (3); infectious disease (3); Insulin resistance (3); lymphoma (3).
A further 136 diseases each share a sentence with HSP90B1 in 3 papers or fewer.